ARID1A (AT-rich interaction domain 1A)
Diseases named in the same sentence as ARID1A in open-access papers (continued):
Sharing a sentence is not in itself a finding about the gene and the disease.
tumor (continued). "We also investigated the association between ARID1A alterations and tumor mutation burden (TMB) level or immune cell infiltrations." (PMID 31949479, 2020). "Remarkably, the loss of ARID1A protein expression in CRC patients was significantly associated with poorly differentiated grade and advanced tumor depth, suggesting the loss of ARID1A protein expression as a predictive marker for poor prognosis CRC." (PMID 32245111, 2020). "Mutations in ARID1A result in the loss of BRG-associated factor 250a (BAF250a), a protein with an important role in cell proliferation and tumor suppression." (PMID 32455595, 2020). "In the one SMARCA4 wild-type tumor (IGR-03) which showed concomitant ARID1A and ARID1B mutations, SMARCA2 expression was higher at the mRNA level (real-time RT-PCR) than in SMARCA4 mutated samples, and interpreted as ambiguous/low at the protein level (IHC)." (PMID 32575483, 2020). "Most strikingly, we found heterozygous loss of two tumor suppressor genes, ARID1A and SMARCE1, components of the chromatin remodeling complex SWI/SNF, and one copy gain of SUZ12 and EZH1, the components of another essential chromatin remodeling complex PRC2." (PMID 32724039, 2020). "Different mutations, like ARID1A and β-Catenin are common in endometriosis and associated cancers, where they can act as tumor suppressors." (PMID 32388637, 2020). "This SMARCA4-WT tumour demonstrated somatic mutations in genes encoding two other subunits of the SWI/SNF remodelling complex: AT rich interactive domain 1 A (ARID1A) and AT rich interactive domain 1B (ARID1B)." (PMID 31844183, 2020). "We found a high frequency (6.2%) of ARID1A, which were associated with significantly higher tumor mutation burden level across various cancers." (PMID 31949479, 2020). "It functions as a tumor suppressor and several therapeutic targets in ARID1A-mutated cancers are currently under development, including EZH2." (PMID 33344089, 2020). "For GC with SRC, univariate analysis showed that age, gender, tumor location, lymphovascular invasion, pathologic T and N categories and ARID1A mutation were significantly associated with OS." (PMID 32824568, 2020). "In BW women, 90% of ARID1A mutant tumours had co-existent PI3K pathway mutations versus 50% of wild-type (wt) ARID1A patients (p = 0.0485)." (PMID 32520976, 2020). "This appeared to be a founder clone, given that the mutation profile was common to the invasive foci as well as the additional high-grade dysplasia harboring ARID1A mutations, thereby suggesting a clonal branch-off during tumor evolution." (PMID 32582528, 2020). "To investigate if SP-2577 promotes tumor immune response in other SWI/SNF-mutant tumor types, we performed ex vivo migration and infiltration of lymphocytes in ARID1A-deficient OCCC cells." (PMID 32649682, 2020). "ARID1A is a tumor suppressor, and its mutated form has been confirmed in a variety of cancers, such as endometrial cancer, and is associated with tumor progression and metastasis." (PMID 32518522, 2020). "There were 36 of 72 (50%) and 52 of 79 (66%) tumors with ARID1A mutation showed tumor stage IV and T3/T4, respectively." (PMID 33344089, 2020). "Deleterious mutations of ARID1A reported across tumor types, led to the prevailing assumption that it behaves as a prototypal tumor suppressor." (PMID 32967217, 2020). "We found a high incidence of ARID1A expression loss in CRC that suggests ARID1A as a tumor suppressor." (PMID 32334542, 2020). "This tumour carried nonsense somatic mutations in ARID1A with putative bi-allelic inactivation (2 frameshifts 556 and 1005/p2285) and a nonsense mutation in ARID1B (one stop gained R1944X)." (PMID 31844183, 2020). "Collectively, data from both the in vivo tumor models and cell culture systems indicate that ARID1A loss resulted in attenuated endogenous TGF-β signaling activities and reduced TGF-β response." (PMID 32483112, 2020).
tumor (continued). "The landscape of MLH1−/− tumors is heterogeneous with only a few shared mutations being detectable among different tumor entities (ARID1A and IDH2)." (PMID 31581674, 2019). "Altogether, these data suggest the intertwined relationship between ARID1A deficiency, ARID1A-mediated pathways, and tumor immunity." (PMID 31277418, 2019). "Given its pivotal tumor suppressive role in vivo, we next sought to explore the consequences of ARID1A loss at the molecular level in an in vitro system." (PMID 31217031, 2019). "A targeted treatment approach involving the inhibition of HDAC6 in tumours with mutated AT-rich interaction domain 1A (ARID1A) showed an improvement of survival using xenograph." (PMID 31146417, 2019). "The positive correlation of ARID1A deficiency with tumor immunity has been attributed to the elevated tumor mutation load caused by the deficiency of DNA mismatch repair that is regulated by ARID1A." (PMID 31277418, 2019). "We found that the correlations between ARID1A mutations and tumor immune signatures were significantly weaker in the MSI-L/MSS subtype than in all GI cancers in STAD-2 and COAD." (PMID 31277418, 2019). "A previous study has shown that inhibition of Ezh2 methyltransferase activity can inhibit tumor cells in an Arid1a-mutated model, highlighting the antagonism of Ezh2 and Arid1a in tumor formation." (PMID 31259687, 2019). "ARID1A has a tumor suppressor function, and inactivating ARID1A mutations occur in various types of cancer." (PMID 31043675, 2019). "Under the notion that ARID1A is a tumor suppressor, several research groups sought to model Arid1a-deficient cancer in mice." (PMID 31217031, 2019). "In this study, using three publicly available GI cancer genomics datasets, we explored the correlation of ARID1A mutations with tumor immunity in GI cancers by a bioinformatic approach." (PMID 31277418, 2019). "The majority of mutations of ARID1A are insertions/deletions, suggesting ARID1A is a tumor suppressor gene." (PMID 31210753, 2019). "Mutations in the chromatin remodelling genes ARID1B and ARID1A were found in 6 (22%) and 4 (15%) tumours, respectively." (PMID 30641862, 2019). "Being a tumor suppressor orchestrating transcription via nucleosome remodeling, the clinical evaluation of the degree and depth of loss of ARID1A remains to be completed in cancers." (PMID 31731647, 2019). "While these have shown some promise, it has become increasingly clear that the context of the tumor must be considered carefully before applying these therapies to ARID1A-deficient cancers." (PMID 31217031, 2019). "ARID1A is a bona fide tumor suppressor and a frequent mutational hotspot in many cancers, including those of the breast, gastrointestinal tract and ovary." (PMID 31581674, 2019). "Our previous study and others had also shown that ARID1A protein loss is more commonly seen amongst MSI cases, and, in this study, 10/22 of MSI subtype tumours showed ARID1A loss by IHC." (PMID 31790410, 2019). "Our bioinformatic analysis revealed that ARID1A mutations had a significant positive association with tumor immunity in GI cancers." (PMID 31277418, 2019). "Collectively, these data suggest that ARID1A mutations lead to MMR deficiency or MSI thereby contributing to the elevated tumor immunity in GI cancers." (PMID 31277418, 2019). "The elevated immune activity in ARID1A-mutated GI cancers was associated with the higher tumor mutation burden and lower tumor aneuploidy level, as well as a higher proportion of MSI cancers in this GI cancer subtype." (PMID 31277418, 2019). "Most cancer-associated mutations in ARID1A appear to be loss-of-function mutations; nonsense or frameshift rather than missense mutations including HCC, suggesting that ARID1A is a tumor suppressor." (PMID 31731480, 2019).
tumor (continued). "For example, in ovarian epithelial cancer (OEC), while Pten/Apc deletion led to the formation of poorly differentiated OECs in mice, the additional deletion of Arid1a caused tumor cells to have a less aggressive, more differentiated epithelial phenotype." (PMID 31217031, 2019). "We observed that ARID1A-mutated GI cancers showed significantly higher TMB (defined as the total number of somatic mutations in tumor) than ARID1A-wildtype GI cancers (Mann-Whitney U test, P < 0.001)." (PMID 31277418, 2019). "AT-rich interactive domain 1A (ARID1A) functions as a tumor suppressor and several therapeutic targets in ARID1A-mutated cancers are under development." (PMID 31043675, 2019). "Somatic inactivating mutations of ARID1A have been reported to impart aberrant chromatin remodeling in a variety of neoplasms, predominantly gynecological cancers." (PMID 31731647, 2019). "These mutations often lead to a loss of ARID1A expression in tumors, and ARID1A has been extensively described as a tumor suppressor in the literature." (PMID 31217031, 2019). "SWI/SNF complex subunit genes have been shown to be mutated in ~20% across all human tumor entities with ARID1A being the most commonly altered subunit gene." (PMID 30138427, 2018). "Approximately 33% of all seromucinous-type tumors present with a mutation in the tumor-suppressor gene ARID1A; therefore, it can be considered as one of the responsible genetic factors." (PMID 30176911, 2018). "ARID1A is also a well-known bona fide tumor suppressor that is frequently inactivated by mutations or reduced in expression due to promoter hyper-methylation." (PMID 29540744, 2018). "Given the nature of the mutations it is generally accepted that ARID1A functions as a tumor suppressor gene." (PMID 29760405, 2018). "In a multivariate Cox Regression analysis this staining combination of ARID1A and ß-Catenin meant a 2.209 fold increased risk for tumor-related death." (PMID 29451900, 2018). "Loss of expression of ARID1A has widespread implications in tumor development, and is associated with lymphatic invasion, MSI, and poor prognosis." (PMID 30008616, 2018). "F3 tumor pieces from an ARID1A wildtype and an ARID1A mutant (homozygous ARID1A 1148* stop-gained mutation) PDX model, were subcutaneously implanted in NSG mice, and were randomized into vehicle control and JQ1 treatment groups." (PMID 29760405, 2018). "Together, these observations open up the possibility of assessing these therapeutic approaches in clinical trials, in particular for tumour types with high frequencies of ARID1A mutations, such as OCCC." (PMID 29659191, 2018). "Overall, 21 ARID1A mutations were identified in 14/43 assessable tumours (33%), the majority of which were predicted to be deleterious." (PMID 29659191, 2018). "The loss of ARID1A expression became even more significant as the tumor–node–metastasis (TNM) stage advanced." (PMID 30097580, 2018). "The work showed that treating ARID1A‐mutated tumours with the small molecule HDAC6 inhibitor, ACY1215, showed a survival benefit in vivo." (PMID 29659191, 2018). "The nature and pattern of the mutations suggest that PPP2R1A functions as an oncogene and ARID1A as a tumor suppressor gene." (PMID 29389895, 2018). "A variety of neoplasms have been discovered to have genomic alterations (GAs) and loss of immunohistochemical (IHC) expression of chromatin remodelers ARID1A (BAF250A), SMARCA2 (BRM), SMARCA4 (BRG1), and SMARCB1 (INI1)." (PMID 31093468, 2018). "An HR of 2.209 for concomitant ARID1A negativity and ß-Catenin n-m-/n+m+ staining of tumors versus other combinations of ARID1A/ß-Catenin meant a 2.209 fold increased risk for tumor-related death for patients who belonged to the first subgroup." (PMID 29451900, 2018). "Two genetically engineered mouse models (GEMM) have been created with ARID1A alterations that led to tumour formation with loss of ARID1A protein expression observed by IHC." (PMID 29659191, 2018).
tumor (continued). "Here, we attempted to show that the frequency of the ARID1A mutation is higher than that previously reported, using pure DNA purified from tumor epithelial cells, using a method we termed ‘liquid microdissection’." (PMID 29599905, 2018). "For example, ARID1A, identified as a tumor suppressor gene, encodes BAF250a, a key component of the SWI-SNF chromatin remodeling complex." (PMID 29780815, 2018). "Possibly, loss of ARID1A activates major signaling pathways that confer an advantage to the tumor cells through enhanced proliferation and/or survival." (PMID 29760405, 2018). "Our results demonstrate a role for ARID1A and ARID1B in maintaining chromatin accessibility and define nucleosome remodeling as a critical function underlying the tumor suppressor role of ARID1A and the synthetic lethal relationship of ARID1A and ARID1B." (PMID 28967863, 2017). "Although noted as a tumor suppressor when mutated, ARID1A’s appearance in the DNA BINDING pathway is consistent with the potential role of chromatin remodeling in selected cancers." (PMID 28792525, 2017). "GATK-based analysis of OV10 also detected a large insertion in PIK3CA, a missense variant in ARID1A (p.Ala532Thr) observed in only 2/25 tumor and 0/100 normal reads, and an NF1 large insertion that introduces a stopgain." (PMID 28852190, 2017). "ARID1A mutations are more frequently identified in these tumors, in comparison to other gynecologic histologies, and loss of ARID1A tumor suppressor function is thought to be an essential component of carcinogenic transformation." (PMID 29093822, 2017). "In an RNAi screen the tumour suppressor gene ARID1A, recurrently mutated in a variety of tumour types, was found to be synthetically lethal in combination with ATR inhibition." (PMID 28448462, 2017). "Of note, one deleterious frameshift mutation affecting ARID1A exon 1 was found in one tumor in addition to SMARCB1 loss." (PMID 28427232, 2017). "Mechanistically, we found that ATR inhibition exploits a pre-existing DNA decatenation defect in ARID1A mutant tumour cells and causes premature mitotic progression." (PMID 27958275, 2016). "We found that the presence of loss-of-function ARID1A mutations in tumour cell lines was associated with greater sensitivity to ATR siRNA (P=0.008, Median Permutation test)." (PMID 27958275, 2016). "Frequent somatic mutations in ARID1A, a tumor suppressor, have been reported in a variety of human cancers." (PMID 27625789, 2016). "An enhanced tumor growth associated with ARID1A downregulation was noted in subcutaneous xenograft model." (PMID 27528032, 2016). "Our results,together with previous mutational and functional studies, suggest ARID1A is a bona fide tumor suppressor." (PMID 25975202, 2015). "Since many types of neoplasms are characterized by loss of ARID1A, further studies are needed to find ways to leverage ARID1A findings for developing targeted therapeutic interventions and understand more in depth the heterogeneity of the results." (PMID 26384299, 2015). "Decreased expression of ARID1A was associated with tumor progression, metastasis, and reduced overall survival in mice and humans." (PMID 25975202, 2015). "ARID1A is highly mutated in tumors and has recently been identified as a novel tumor suppressor in different cancer types." (PMID 26334097, 2015). "For example, in the right kidney, somatic mutations were identified in ARID1A in tumor one (category 2), and in IDH2 in tumor two (category 3)." (PMID 25159823, 2014).
tumor (continued). "ARID1A is a tumour suppressor gene and encodes BAF 250a protein that is involved in the multiprotein SWI/SNF chromatin-remodelling complex." (PMID 24804229, 2014). "The list of tumor types in which ARID1A mutations have been identified keeps expanding and increasing evidence indicates that epigenetic silencing can also contribute to its functional inactivation." (PMID 23650517, 2013). "We also analyzed the expression of cytokeratins in the same set of tumor and find, using unsupervised clustering, that tumors with ARID1A loss of expression are generally KRT5/6-low." (PMID 23650517, 2013). "ARID1A expression score was significantly lower in more aggressive tumors (ANOVA P = 9.9×10−6; KW P = 3×10−5), in agreement with the observation that ARID1A mutations are more common in this tumor subgroup." (PMID 23650517, 2013). "Future studies will be required to define the molecular mechanisms by which loss of ARID1A expression contributes to tumor development in OCCC." (PMID 21614196, 2010). "In xenografts, β‐catenin‐∆E3 dramatically accelerated tumor growth in ARID1A‐deficient cells." (PMID 41133886, 2026). "Under the process of cell clonal evolution in Arid1a‐deficient liver tissues, cells with Ctnnb1 mutations may further expand and promote tumor formation." (PMID 41133886, 2026). "ARID1A is frequently mutated in both non‐malignant tissues and cancers, but its role in tumor development after exposure to genotoxic carcinogen remains unclear." (PMID 41133886, 2026). "ARID1A, a frequently mutated tumour suppressor, interacts with TOP2A to maintain mitotic fidelity." (PMID 41578412, 2026). "Dasatinib may exert inhibitory effects on ARID1A‐deficient tumour cells by regulating the cell cycle regulatory network associated with cyclin—dependent kinase inhibitor 1A (CDKN1A) and RB1." (PMID 39779467, 2025). "Indeed, a phase I and a phase II clinical trial have tested the ATR inhibitor ceralasertib (AZD6738) in patients with ARID1A loss in different cancers and show durable anti‐tumor activity." (PMID 40170512, 2025). "Notably, in the context of tumor immunology, GC patients harboring ARID1A mutations exhibit higher levels of CD8+ T cell infiltration and derive greater benefit from immunotherapy." (PMID 40406134, 2025). "Thus, ARID1A mutations play a pivotal role in the pathogenesis of PDEECs, contributing to tumor development through the disruption of chromatin remodeling, genomic instability, and aberrant cell cycle regulation." (PMID 40072110, 2025). "Indeed, the density of CD4+ and CD8+ tumor-infiltrating lymphocytes (TILs) was also remarkably increased in the ARID1A-deficient CRC tumors that received RT and CHK1 inhibitor treatment." (PMID 40750787, 2025). "We therefore hypothesize that mutating one allele of ARID1A may benefit the tumor, while a second hit would indeed decrease proliferation, harming tumor development." (PMID 40170512, 2025). "This indicates that in early stages it may be beneficial for the tumor to mutate ARID1A for increased proliferation, whereas later other effects may be tumor supportive." (PMID 40170512, 2025). "Most studies associate ARID1A loss with poor prognosis and tumor progression, recent studies suggest it may also increase susceptibility to specific therapies." (PMID 41001036, 2025). "ARID1A expression was also associated with somatic mutations in tumor driver genes." (PMID 39796161, 2025). "This suggests that ARID1B activity may be essential for tumor growth in the context of ARID1A mutation or downregulation." (PMID 40671262, 2025). "The loss of ARID1A protein was heterogeneous in GC tumor tissue, thus suggesting that ARID1A mutations may be a later event of gastric carcinogenesis." (PMID 39796161, 2025).